C3 (complement C3)
Diseases named in the same sentence as C3 in open-access papers (continued):
Sharing a sentence is not in itself a finding about the gene and the disease.
tumor (continued). "The demographic and baseline characteristics were almost comparable between the two groups (P > 0.05), except plasma levels of C3 and C4, and tumor histology (P < 0.05)." (PMID 31928530, 2020). "Overexpression of C3 by tumor cells in cSCC in vivo has also been noted and stronger staining intensity for C3 was noted in RDEBSCC." (PMID 31331124, 2019). "Of note, the emPAI % values of complement C3 and apolipoprotein C‐III were associated with the tumor progression and prognosis of HCC, as galectin‐3‐binding protein in CCA and 72 kDa inositol polyphosphate 5‐phosphatase in cHCC‐CCA." (PMID 31136099, 2019). "Among all the complement elements with potential pro-cancer activities, C1q, C3-derived fragments, and C5a are recognized as major modulators of tumor progression." (PMID 31031765, 2019). "PTX3 knockout goes along with increased C3 deposition in neoplastic tissues that correlates with an increased tumor progression." (PMID 31533326, 2019). "In REACTOME pathway analysis, the most highly correlated pathway was activation of the C3 and C5 complement system in the tumor, which has a role in the regulation of the cancer microenvironment and has been suggested as a target in cancer immunotherapy." (PMID 31652813, 2019). "Expression of anaphylatoxin receptors and production of C3 by cancer cells suggests, that anaphylatoxin receptor-mediated tumor growth is not only mediated by an immunomodulatory effect of C3, but by direct autocrine effect." (PMID 31331124, 2019). "More relevant to time of day, some inflammatory mediators (Myd88, Cd4, Tlr9, Cd38, C3, Ly96) demonstrated nyctohemeral (day versus night) differences in control brain tissues that were abolished in tumor-bearing and/or tumor-resected mice." (PMID 31019214, 2019). "High expression of the C3 protein in cSCC cell lines and in C3a releases C3 cleavage, which induces tumour growth via receptor C3aR." (PMID 30825266, 2019). "Complement C3 activation fragments can also precondition the tumor microenvironment toward immunosuppression." (PMID 31031765, 2019). "The incomplete effects of mAbs on tumor cells are partially due to the existence of protective complement inhibitory mechanisms that interfere with mAb and Complement 3 (C3) interactions with cancer cells." (PMID 30987235, 2019). "The results showed that C3 mRNA expression was upregulated in all tumour cell lines and was more than 4.5 times higher in A431 and SCC13 cells." (PMID 30825266, 2019). "Conversely, macrophages express receptors for activated C3 and C5, respond to activated C3a and C5a mediators at the site of local inflammation, and maintain angiogenesis in tumour tissues." (PMID 30841875, 2019). "Therefore, it might be conceivable that tumor-associated increased oligomannose N-glycan levels could derive from an increased expression of oligomannose carrying glycoproteins and the increased presence of complement C3." (PMID 29619343, 2018). "Different results were obtained using a syngeneic mouse model of ovarian cancer which showed similar growth in wild type and C3−/− mice due to secretion of C3 by tumor cells that exerts a stimulating effect on cell proliferation." (PMID 30319647, 2018). "The multidomain protein complex, SST3‐Avi‐C3, retargets C3 enzyme into non‐small cell lung A549 cancer cells and exhibits exceptional tumor inhibition at a concentration ≈100‐fold lower than the clinically approved antibody bevacizumab (Avastin) in vivo." (PMID 30128225, 2018). "In mice, modulating intrinsic C3 activity (the equivalent of C3b-mediated CD46 engagement in humans) in tumor-infiltrating lymphocytes can promote tumor progression." (PMID 30305631, 2018). "The therapeutic effect of the Abs was largely dependent on C activation, as revealed by the increased deposition of C3 and C9 in tumor masses, and also by local recruitment of macrophages and NK cells." (PMID 30319647, 2018).
tumor (continued). "TWIST1 and C3 colocalized at the invasive tumor edges, and in the neural crest and limb buds of mouse embryos." (PMID 30061895, 2018). "Specifically, postoperative decreased C3 levels (<0.75 mg/mL) and advanced tumor stage (stage III/IV) were correlated with a poor prognosis for GC patients." (PMID 29062836, 2017). "TIL155-C2 and C4 also recognized allogeneic 1297mel tumor cells, whereas C3 recognized allogeneic 1359mel cells." (PMID 25993655, 2015). "Usually, the antigen-antibody complex formed through an antibody combining with a tumor cell antigen is able to activate C1 and C4, thereby further activating C3, and then activating a complement cascade to kill tumor cells in vivo." (PMID 25017204, 2014). "We now show that blocking IDO results in C3-dependent tumor destruction, uncovering an unanticipated link between IDO and complement." (PMID 25054064, 2014). "By contrast, C3−/− animals showed a similar level of tumor protection as WT controls, ruling out a major role for complement in the anti-tumor effect." (PMID 20844763, 2010). "Tumour C3 protein levels, already elevated after individual PDT or γ-inulin treatments, increased much higher after their combination." (PMID 17146472, 2007). "High levels of C activation products in the AF samples and deposits of C1q and C3 on the isolated tumour cells indicate that the AF C system has become activated in vivo." (PMID 15726105, 2005). "Complement resistance of both malignant tumour cells and normal cells is mediated by membrane-bound C regulatory proteins that either limit the formation of the C3/C5 convertase enzymes, or the assembly of the MAC." (PMID 15726105, 2005). "GO analysis revealed that complement C3 was involved in the anti-tumor effect." (PMID 40596619, 2025). "Tumour cell‐derived complement proteins, such as C3, which inherently inhibit anti‐tumour immunity, could potentially serve as effective targets for cancer immunotherapy, enhancing the anti‐tumour immune capabilities of the complement system." (PMID 40847563, 2025). "Notably, metastatic LMSCs exhibited upregulated complement C3 expression when stimulated with Th2 cytokines, which led to increased neutrophil recruitment to pre-metastatic sites, promoting tumor metastasis." (PMID 40634316, 2025). "Complement C3 has been shown to be involved in the growth of tumor cells in CSF." (PMID 39819494, 2025). "Importantly, the analysis of tumor specimens included here revealed direct correlations between C3 expression, BMI, and disease outcome." (PMID 39964754, 2025). "Functional assays in BLCA cell lines or organoid models, including C3 or C5 inhibition, could further reveal how complement activation impacts tumor progression, immune infiltration, and immunotherapy response." (PMID 40283026, 2025). "The aim of our study was to evaluate whether delivery of MUC1 100mer peptide and TLR agonists with C3-liposomes would effectively protect mice against a tumor challenge using MUC1-expressing tumor cells." (PMID 40284463, 2025). "After demonstrating that the coculture of OC cells with adipocytes stimulates cell proliferation via C3 activation in vitro and that C3 is essential for tumor progression in vivo, we sought to determine the relevance of the complement cascade elements’ expression in human tumors." (PMID 39964754, 2025). "To further study the potential role of C3 in tumor progression, we used i.p. xenografts." (PMID 39964754, 2025). "Additionally, C3 deletion in high-C3-expressing tumor cells has been shown to enhance the efficacy of anti–PD-L1 therapy, suggesting its potential as a therapeutic target." (PMID 40396123, 2025). "The expression of C3 allows their involvement in complement activation within the tumor microenvironment, thereby influencing tumor cell lysis and immune cell activation.ALOX5AP and LTC4S participate in arachidonic acid metabolism, modulating inflammatory responses and immune cell functions." (PMID 41394809, 2025).
tumor (continued). "In this study, C3 deficiency or C5aR inhibition impaired tumor growth and tumors lacking C5aR signaling showed minimal infiltration by Gr1+ CD11b+ MDSCs compared with WT tumors." (PMID 38786066, 2024). "First, the targeting of Bi by mAb increased the levels of C3 in tumor tissues and serum." (PMID 39010088, 2024). "Given the high immunogenicity of C3 tumor cells, we propose that C3 may contribute to enhanced immune infiltration within the TME." (PMID 39664386, 2024). "C3 expression was verified by immunofluorescence of 308 tumor samples." (PMID 38525245, 2024). "Costaining of the panmacrophage marker F4/80 with C3 and the tumor cell marker Olig2 revealed that C3 expression itself was found in areas staining positive for both F4/80+ and Olig2+ cells, indicating that C3 expression can conceivably come from both these cell types in murine GBM." (PMID 39172519, 2024). "C3 inhibition in vivo slowed tumor growth, and altered macrophage and T cell infiltration." (PMID 38525245, 2024). "Mechanistically, CDK9 inhibition leads to compensatory activation of ERK‐MYC signaling, accompanied by the recovery of proto‐oncogenes, upregulation of immediate early genes (IEGs), stimulation of the complement C1r‐C3‐C3a cascade, and induction of tumor immunosuppression." (PMID 39254172, 2024). "MBL, a lectin that recognizes fungal infections and activates the pathway of the complement cascade, is essential for carcinogenesis development, while C3aR knockdown in tumor cells or deletion of MBL or C3 in the extra‐tumoral compartment are protective against tumor growth." (PMID 38882486, 2024). "Complement activation leads to tumor cell opsonization by C3-derived opsonins (C3b, iC3b and C3dg) and the generation of potent pro-inflammatory mediators (C3a and C5a), which in turn recruit and activate immune cells with phagocytic properties (neutrophils and macrophages)." (PMID 38242872, 2024). "Then, the complex interaction between the tumor cells secreting the other components of the complement (C1r, C1s, C3, and C4), the MDSCs, and exhausted T lymphocytes leads to proliferation, increased tumor invasiveness, and neoangiogenesis, which ultimately results in tumor progression." (PMID 38339243, 2024). "Therefore, c1 and c15 can be identified as normal epithelial cells, while c3, c4 and c7 were intermediate cells experiencing normal-to-tumor transition." (PMID 37950728, 2023). "We hypothesized that tumors with elevated expression of C3-specific genes were infiltrated with a relatively high proportion of tumor-reactive CD8+ T cells and thus labeled them as pTRT cell-high BrM." (PMID 37217652, 2023). "Furthermore, deletion of MBL or C3 in the extra-tumoral compartment or knockdown of C3ar in tumor cells were both protective against tumor growth in mouse models." (PMID 37034706, 2023). "Intracellular activation of tumor cell-derived C3 inhibited CD8+ T cell infiltration and function by driving the accumulation and immune-suppressive activity of tumor-associated macrophages (TAMs) in a C3a-C3aR-dependent manner through the C3a-C3aR-PI3Kγ signaling pathway." (PMID 36969185, 2023). "Several immune checkpoint genes (HAVCR2, CD47, LGALS9, and CD276) were gradually upregulated along the DC differentiation trajectory, especially at the late stage, revealing that C3-DC might suppress tumor immunity." (PMID 36788228, 2023). "Increased expression of C3 could indicate the activation of the complement cascade pathway: the immunity system is activated and can destroy tumor cells." (PMID 37371512, 2023). "In addition, multiple components of the complement system, a central mediator of RT-induced tumor-specific immunity, were upregulated — specifically, C1qa, C1qb, C1ra, C1s1, C3, C3ar1, C4b, and C6." (PMID 37345658, 2023). "To this end, we examined the deposition of C1q, C3 and C9 in the tumor masses using IF." (PMID 38017492, 2023).
tumor (continued). "Our data support the paradigm that the GBM tumor environment may favor elevated expression of C components such as C3 and C3aR." (PMID 37174113, 2023). "In conclusion, suppression of DAPK1 may accelerate tumor growth and result in the upregulation of C3, TIMP-1, and AHSG expression and downregulation of KNG1 expression." (PMID 35935258, 2022). "C3 secreted from these cells is cleaved in the extracellular space and C3a, generated through this cleavage, recruits C3aR expressing macrophages that supress antitumor immunity and accelerate tumor growth." (PMID 35860237, 2022). "Except for fibroblasts, a total of 937 endothelial cells were also obtained, which were subclustered into five subsets, including extra-alveolar capillary ECs (Endo-C1; EDN1+), tumor ECs (Endo-C3; INSR+), and other ECs (Endo-C2, ICAM1+; Endo-C4, MAP1B+; Endo-C5, CXCR4+)." (PMID 36046337, 2022). "However, inducing C3 expression appears to be a critical event in cancer progression as silencing C3 inhibits tumor progression." (PMID 36686777, 2022). "Importantly, the deletion of C3 from the tumor cells enhances the efficacy of anti-PD-L1 therapy in this model." (PMID 35860237, 2022). "Additionally, high levels of THY1/PD-L1 and complement components in T1 tumors provoke an immunosuppressive tumor microenvironment, suggesting an inflammatory phenotype, and depletion of C3 in tumor cells enhanced the efficacy of anti–PD-L1 treatment." (PMID 35626021, 2022). "The constitutive C3 deficiency did not result in reduction of tumor growth in this model, which further underscores those functions of complement in cancer are highly context and model dependent." (PMID 35860237, 2022). "Silencing cancer cell-specific C3 inhibited tumor growth In vivo." (PMID 36686777, 2022). "Depletion of C3 in tumor cells enhanced the efficacy of anti–PD-L1 treatment." (PMID 35626021, 2022). "Depletion of C3 in tumour cells sensitizes the tumour to anti-PDL1 treatment." (PMID 36341431, 2022). "In an orthotopic HCC mouse model, Wang and colleagues reported that PIWIL1-mediated increased secretion of C3 from HCC promoted the infiltration of MDSCs in the tumour microenvironment of HCC via the p38/MAPK pathway, which suppressed T-cell proliferation and facilitated HCC development." (PMID 36341431, 2022). "Together with the high local expression of C3, this suggests that complement could be activated via the alternative pathway in the tumor microenvironment." (PMID 35053469, 2022). "To further understand how C3 might be promoting tumor development in an inflammatory microenvironment, we investigated the role of C3 during TPA-driven skin inflammation without the application of carcinogen." (PMID 32682912, 2021). "Intriguingly, the deficiency of C3aR1, C5aR1, or C5aR2 generated opposite results to the deficiency of C3, with a modest increase in tumor number and growth, whereas the MAC did not play a key role either way." (PMID 32682912, 2021). "This is also supported by our data on high expression of C3 protein in tumour cells in BCa." (PMID 33658651, 2021). "C3 interacts with the C3a receptor (C3aR) on the epithelial cells of the choroid plexus, perturbs the barrier function and allows the passage of mitogen factors, such as amphiregulin, that drive tumor growth in leptomeninges." (PMID 34207653, 2021). "Further, our correlation analysis suggests that these associations between the expression levels of C3, C3AR1, and C5AR1 and tumor immune infiltration could possibly enhance tumor immune evasion via dysfunctional T-cell phenotypes." (PMID 34439277, 2021). "Radiotherapy failed to control tumours in mice deficient in either C3, C3aR or C5aR, indicating a functional role for complement in achieving treatment efficacy." (PMID 33802004, 2021).
tumor (continued). "COLEC12 could reduce TLR4 expression, weaken NF‐κB and C3 signaling pathway to release inflammatory factors downstream, restrain immune defense to tumor cells, inhibit apoptosis of tumor cells, and cut down lives of mouses." (PMID 32822099, 2020). "Although heterogeneous relative to tumor type, complement proteins expressed by malignant cells are variable; in general, tumor cells express low C8 and C9 but highly express C3 and the regulators factor H, factor I and especially the membrane regulators CD46, CD55 and CD59." (PMID 33147799, 2020). "It suggested that C3 might be expressed by the neoplastic epithelia as a component of tumor pathology, and thereby contribute to local immune responses." (PMID 31928530, 2020). "However, blocking tumor cell derived complement C3 enhanced antitumor functions by enhancing the efficacy of anti–PD-L1 treatment, suggesting C3 in combination with ICIs as a potential target for HCC therapy." (PMID 33718121, 2020). "However, in contrast to the previous work on C1q functions in tumors, C1q in RCC seems to trigger the classical pathway because C1q deposits on tumor cells co-localized with IgG and C4d, and C3 cleavage products were also detected in these tumors." (PMID 33271774, 2020). "Moreover, the expression levels of C3, CR4, and C5aR1 were also strongly correlated with various immune marker sets, such as those of tumor-associated macrophages (TAMs), M1 and M2 macrophages, T cell exhaustion, Tregs, and DCs, in STAD." (PMID 33614473, 2020). "Strikingly, for genes in cluster ii), which are specifically up-regulated in AAS, high expression of 7 of the top 10 genes (C3, CD74, HLA-DRA, STRA6, IGFBP4, PIGR, and TNIP1) was strongly associated with better cumulative survival than tumours with low expression of these genes." (PMID 32218455, 2020). "Among all the complement elements that may have the pro-cancer activities, C1q chains, C3-derived fragments, and C5a are likely the most important modulators of tumor progression." (PMID 33033253, 2020). "Finally, complement component 3 (C3) gene expression was unique in that tumor- and tumor-resected mice displayed a time-of-day difference opposite to that of controls: elevated in the dark phase as opposed to elevated in the light phase." (PMID 31019214, 2019). "Strikingly, blocking tumor-derived complement C3 is sufficient to enhance antitumor immunity." (PMID 31805946, 2019). "Furthermore, stepwise Cox regression analyses revealed that HCC patients with a hybrid glycoform at Asn85 of complement C3 had a lower postsurgery tumor recurrence rate or mortality rate than those with a low amount of complement C3 protein." (PMID 31136099, 2019). "C3 plays a key role in complement system and could support tumor growth by immunosuppression as well." (PMID 31118022, 2019). "In addition, only tumor cells treated with the combination are likely to have a sufficient number of cell-bound antibodies to induce efficient C3 opsonization, required to initiate complement-mediated-cytotoxicity and macrophage-mediated tumor cell killing." (PMID 30922362, 2019). "Whether intracellular activation of C3 contributes to the effect of tumor cell-derived C3 on cSCC cells remains to be elucidated." (PMID 31331124, 2019). "Deletion of C3 in tumor cells also inhibits M2 polarization." (PMID 31031765, 2019). "Other complement elements, such as C1q, C3, or C3a, may be also targeted to re-educate the tumor microenvironment and sensitize it to the subsequent administration of immune checkpoint blockers." (PMID 31031765, 2019). "In addition, tumor inflammatory microenvironments were found to contain the complement-activating components C3, C4, C5, C1q, and MAC in many cancer models." (PMID 31236404, 2019). "In addition, evidence has shown that the genetic deletion of C3 or C5aR and pharmacological blockade of C5aR impaired the ability of T cells to overcome the endothelial barrier, infiltrate tumors, and control tumor progression in vivo." (PMID 31787848, 2019).